TYR (tyrosinase)
Diseases named in the same sentence as TYR in open-access papers (continued):
Sharing a sentence is not in itself a finding about the gene and the disease.
melanoma (continued). "The antigens targeted by these autoreactive melanocyte-specific cytotoxic lymphocytes derived from proteins of the melanogenic pathway, such as gp100, (Melanoma antigen recognized by T cells 1) MART1, tyrosinase, and tyrosinase-related proteins 1 and 2, thus mediating melanocyte destruction." (PMID 36902341, 2023). "In addition, it exerts whitening effects by inhibiting tyrosinase activity and melanin production in B16F10 melanoma." (PMID 37570831, 2023). "In the original melanoma patient from which TIL1383I was cloned, upregulation of the tyrosinase gene may have served a similar purpose, allowing an otherwise quiescent T cell to expand, drive tumor infiltration, and contribute to tumor rejection." (PMID 36424374, 2022). "Similarly, in the present study, ITMFAb attenuated tyrosinase expression and activity and melanin production in α-MSH-stimulated B16BL6 melanoma cells." (PMID 36422527, 2022). "Vitiligo and antitumor responses in melanoma reportedly depend on CD8+ T cells that recognize identical antigens, so-called melanocyte/melanoma-shared antigens (MSA), including Melan-A, tyrosinase, and premelanosome (PMEL), and can reduce melanoma mass and prevent tumor recurrence." (PMID 35432377, 2022). "Since melanoma express their own tumor Ags, such as NY-ES0-1, gp100, and tyrosinase, the increase in enzymatic activity by GILT-expressing melanoma cells could be exploited for the induction of tumor Ag-specific T cells." (PMID 35162988, 2022). "Lastly, evaluation for RNA levels of TYR, CD34, and CALD may help to further differentiate between canine oral amelanotic spindloid malignant melanomas and oral soft tissue spindle cell sarcomas." (PMID 35448673, 2022). "The key enzyme of this pathway is tyrosinase, which is always retained in melanoma cells in vivo, even when the whole tumor becomes non-pigmented and amelanotic." (PMID 36428680, 2022). "We observed a significantly lower expression of the melanocyte markers TYR and TRP1 and a higher expression of the NCC marker p75, which leads to the assumption that a knockdown of ADCK2 led to a dedifferentiation of melanoma cells, prompting them to adopt a more aggressive phenotype." (PMID 35205819, 2022). "Similarly, the effect of epicatechin in the treatment of melanoma was studied, using the melanoma cell line B16F10 and it was observed that it decreases melanin synthesis and inhibits tyrosinase activity, thus participating in the melanogenesis process." (PMID 35050083, 2022). "In the skin whitening activity assay, all of the three CMs displayed significantly high inhibitory activities against tyrosinase, and LF101 and LPP401 showed markedly higher suppressive activities on the α-MSH-induced melanin contents than LP202 in B16F10 melanoma cells." (PMID 35601147, 2022). "However, we noted that while MITF expression was similar in primary tumors and metastases, a number of well‐characterized MITF target genes (e.g., TYR, TYRP1, MELANA, PMEL) were significantly more highly expressed in primary melanomas than in metastases." (PMID 35771179, 2022). "A study reported that 0.25–0.5 mM α-arbutin reduced melanin content and decreasing tyrosinase activity in a dose dependent manner, but 0.25–1 mM α-arbutin did not influence cell proliferation in cultured human melanoma cells." (PMID 35326152, 2022). "All of the isolated metabolites were evaluated for their tyrosinase inhibitory and cytotoxic activities, and it was revealed that kazinol F-4′′-O-β-d-glucopyranoside had the strongest anti-tyrosinase activity with no cytotoxic activity against melanoma cells." (PMID 35335241, 2022). "Next, we used the octapeptide at 50 μg/mL, the same as that used in the in vitro tyrosinase inhibitory assay, which also did not significantly affect the melanoma cell viability." (PMID 35745603, 2022).
melanoma (continued). "In vitro studies using B16F10 cells (a melanoma cell line) showed that analogs 1, 2, 3, and 6 inhibited cellular tyrosinase and melanin production more than kojic acid did, without perceptible cytotoxicity." (PMID 35624809, 2022). "In vivo experiments showed that GM could effectively inhibit the expression of tyrosinase, regulate the proportion of CD4+ T cells, CD8+ T cells, and regulatory T cells (Treg cells) in tumors, and significantly suppress melanoma growth." (PMID 35875081, 2022). "Melanoma Ags MART-1, NY-ESO-1, gp100, and tyrosinase are broadly expressed in human tumors." (PMID 35162988, 2022). "This study investigated the effects of tyrosinase inhibitory peptide FTGML, derived from grass carp fish scale gelatin, on the melanin inhibitory signaling pathway and intracellular antioxidant activity in murine B16F10 melanoma cells." (PMID 35159541, 2022). "PMEL, S100B, SERPINE2, TYR, and PRAME were highly expressed in tumor cells and could be the marker genes for melanoma." (PMID 35646893, 2022). "Indeed, we found a significant time-dependent Cpd1-induced transcription of the melanocytic master regulator MITF and other downstream differentiation genes like DCT, TYR, and MART-1/MLANA in pigmentation-competent melanoma cells." (PMID 35650266, 2022). "Tyrosinase % inhibition at 100 μΜ and their IC50 values in B16F10 and B16F1 melanoma cell lines." (PMID 36009312, 2022). "Op-AG-NE showed promising cytotoxicity effects on the human malignant melanoma- (A375 cells) and non-melanoma cells (A-431 cells) via apoptosis induction with a high selectivity index and also inhibited intracellular tyrosinase activity in the A375 cells." (PMID 34452250, 2021). "HMB-45, SOX10, and tyrosinase, but not melan-A, proved to differentiate the nevi from malignant melanomas successfully, with high specificity." (PMID 34206844, 2021). "For instance, tyrosinase, gp100, MAGE-A3, MAGE-C2 have been identified as TAAs for melanoma." (PMID 33632261, 2021). "All four known melanoma cell markers were candidate cell marker genes for cell type H, and MLANA, PMEL, and TYR were candidate cell marker genes for cell type G. In addition, the protein-coding gene PMEL was a candidate cell marker gene for five cell types (all cell types except C, D, and F)." (PMID 34784909, 2021). "As the two members of the pan-melanoma cocktail, HMB-45 and tyrosinase, proved to differentiate benign vs. malignant lesions, together with SOX10, the present paper suggests that, in the conventional cocktail, melan-A should be substituted by SOX10, for a better differentiation." (PMID 33801642, 2021). "They showed that α-arbutin decreased melanin content and TYR activity in cultured human melanoma cells, at a concentration below 1.0 mM, without significant effects on cell growth and TYR mRNA level." (PMID 34356362, 2021). "Four known melanoma cell marker genes, MITF, MLANA, PMEL and TYR, were obtained from CellMarker." (PMID 34784909, 2021). "CD40L:CD28-transduced TCR-T58 T cells were co-cultured with the melanoma tumor cell line (SK-Mel23), which provides the activation stimulus through the TCR-peptide/MHC interaction (HLA-A2/tyrosinase, which is the ligand for TCR-T58) and expresses CD40 endogenously." (PMID 34912334, 2021). "On the other hand, JUA and BTL did not directly inhibit mushroom tyrosinase activity in vitro or melanogenesis in B16F10 melanoma cells and zebrafish larvae." (PMID 34299326, 2021). "Our results in MNT-1 cells show that DOLE seemed to promote the export of melanosomes, in the absence of changes in the levels of melanin within the cells or the intracellular tyrosinase activity, which is similar to our results obtained earlier with B16F10 mouse melanoma cells." (PMID 33799651, 2021).
melanoma (continued). "The anti-melanogenic capacity of pseudoalteromone A was demonstrated by assessing the intracellular and extracellular melanin content and cellular tyrosinase activity in the B16 cell line, Melan-a mouse melanocyte cell line, and MNT-1 human malignant melanoma cell line." (PMID 34822483, 2021). "C3G, EC, and CH, exhibit no substantial cytotoxicity (100 μg/mL) on murine melanoma cells marking them as ideal candidates for the assessment of mammalian tyrosinase inhibition by comparison to ARB inhibitor." (PMID 34969954, 2021). "The expression of differentiation antigens that are commonly present and have been previously used as immunological targets in melanoma, namely, TYR (tyrosinase) and MLANA (Melan-A/MART1), were compared with CTAG1A and ROPN1 or ROPN1B in our panel of melanoma cell lines." (PMID 33918976, 2021). "We found that PA significantly inhibited melanin synthesis and tyrosinase activity in a dose-dependent manner, and did not have a cytotoxic effect on melanoma cells." (PMID 33917915, 2021). "Another 5-HT derivate, N-dihydroxyphenil-acylserotonin was able to suppress melanin with no cytotoxicity on B16 melanoma cell lines via the inhibition of tyrosinase through the 5-hydroxyindole moiety." (PMID 34068618, 2021). "Secondly, an in vitro B16F10 melanoma cell study was conducted and it was concluded that THC could decrease the activity of tyrosinase, which is the key enzyme responsible for melanin synthesis." (PMID 34452146, 2021). "Tyrosinase expression is typical for melanoma cells and melanocytes, with neither of them found in healthy patients’ blood." (PMID 34575876, 2021). "The presence of tyrosinase protein was confirmed in both Ab and B16F10 melanoma cells." (PMID 33506271, 2021). "In addition to MITF, other melanocytic genes (such as TYR, DCT, MART-1) are also upregulated in the proliferative phenotype of melanomas." (PMID 34698090, 2021). "Previous studies have established the role of tyrosinase and/or TYRPs in B16F10 melanoma cells." (PMID 33344501, 2020). "CAPE is metabolized by tyrosinase to CAPE-SG conjugate (caffeic acid glutathione conjugate) and CAPE-quinone, which inhibit GST catalytic activity and play major roles in the selective inhibition of GST in melanoma cells." (PMID 32456290, 2020). "In concordance with this, it was observed that non-mutated melanoma associated antigens, MART-1/Melan-A, gp100, and tyrosinase, are heterogeneously expressed across melanoma cells." (PMID 33256089, 2020). "Although the cellular melanin content was tested similarly in MSH-activated B16 melanoma cells, the authors did not determine the cellular tyrosinase inhibition activity of FLA and FLB." (PMID 32731323, 2020). "This is a prospective, randomized, open-label phase 2 study (NCT02285413) including stage III and IV melanoma patients receiving 3 biweekly vaccinations of gp100 and tyrosinase mRNA-loaded monocyte-derived DCs with or without cisplatin." (PMID 31980913, 2020). "In healthy individuals (and not in melanoma patients), melanoma-specific T lymphocytes displaying a strong reactivity against peptides of melanoma antigens Tyrosinase–MAGEA3–Melan-A/Mart-1–Pmel 17gp100 and NY-ESO-1 have been identified." (PMID 32028565, 2020). "Thus, the inhibitory effects of IPA on tyrosinase activity and melanogenesis were examined in a zebrafish in vivo model and murine B16F10 melanoma cells." (PMID 32957728, 2020). "In our previous study, we reported that AP inhibited mushroom tyrosinase and the generation of melanin pigments in a B16 mouse melanoma cell study in vitro, which was a non-UV irradiation system." (PMID 32294883, 2020). "This study aimed to compare the rates of rare alleles in albinism genes in patients with AHM, PM only, or with no melanoma history and found differences in rates of TYR/OCA1 and OCA2 variants." (PMID 32966289, 2020).
melanoma (continued). "Choosing SCM as the microenvironment for melanoma cells was crucial with transcriptomic analysis that serum present in the medium drastically reduces expression of MITF-M and 74 MITF-dependent genes, including TYR, DCT, and MLANA." (PMID 31354817, 2019). "Also, because LDE-EA inhibited melanin synthesis and tyrosinase expression, we evaluated if LDE-EA is reduced the production of cAMP, which induces the expression of MITF, in B16 melanoma cells." (PMID 30695994, 2019). "Melanoma cell destruction was also well documented biochemically, showing a great reduction in α-mannosidase and tyrosinase activities in non-treated melanomas taken six months after devitalization of another cutaneous melanoma." (PMID 31717496, 2019). "ABO induced dose‐dependent reductions in tyrosinase activity and melanin production in both the melanoma cells and zebrafish, without affecting viability." (PMID 31660135, 2019). "In addition, compounds 1 and 3 inhibited cellular tyrosinase activity, decreased tyrosinase protein expression levels, and reduced the melanin content in α-MSH-treated B16F10 melanoma cells in a concentration-dependent manner." (PMID 31108882, 2019). "MITF level and expression of MITF-dependent pigmentation-related genes, MLANA, PMEL, TYR, and DCT, in drug-naïve and vemurafenib- or trametinib-treated patient-derived melanoma cell lines and their drug-resistant counterparts were analysed and referred to genomic alterations." (PMID 31354817, 2019). "In a clinical trial in patients with stage IV melanoma treated with DCs loaded with a multi-peptide (WT1, gp100, tyrosinase, and MAG-E3 or MAGE-A2) combined with paclitaxel (175 mg/m) and carboplatin (area under the curve 5), an OS of up to 24 months was observed." (PMID 31020037, 2019). "Four phenols, BP, PP, PhP, and TBP, reduced tyrosinase protein levels in pigmented melanoma cells, whereas the other phenols did not affect tyrosinase levels." (PMID 30767390, 2019). "Surprisingly, 17-AAG also stimulated melanin production in SK-Mel-30 cells and enhanced TYRP1 and DCT expression without stimulating TYR production in all three BRAFWT cell lines studied as well as in B16F10 mouse melanoma cells." (PMID 29481571, 2018). "The first genetic engineered melanoma mouse model was the transgenic mouse model—Tyr-SV40, that exhibited overexpression of SV40 T antigen (Tag) under the control of melanocyte-specific tyrosinase (Tyr) gene promoter and developed melanoma spontaneously or after UV irradiation." (PMID 29795011, 2018). "Moreover, several molecular abnormalities and signaling pathways described in specific human melanoma subtypes can be found in canine melanoma, including phosphorylated forms of AKT and ERK1/2, alterations of the receptor tyrosinase KIT and PTEN." (PMID 29534457, 2018). "Melanoma was the first model to reveal CD4+ and CD8+ cellular specificity to cancer differentiation antigens gp100 and tyrosinase, suggesting the immunogenicity of the tumor and the ability of the patient’s own immune system to recognize and activate a specific immune response against cancer cells." (PMID 29534457, 2018). "That amelanotic tumor was tyrosinase negative, grew significantly slower than the parental Ab melanoma, and had a different metastasis pattern that was similar to the Ma melanoma." (PMID 29614755, 2018). "Most recent explorations of the functional role of CD271 in melanoma have clearly demonstrated that CD271+ cells comprise a special subtype of melanoma cells with stem-like properties and a lower expression of melanocyte-markers such as MART1, MITF and tyrosinase." (PMID 30053879, 2018). "Since we observed a close correlation between the Wnt3a-CM or PKF115–584 treatment and the expression of pigmentation related genes (DCT, TYR, TYRP1, MITF) in our SKMEL28 microarray data, we analyzed the TCGA melanoma RNAseq expression data concerning MLANA expression." (PMID 29454361, 2018).
melanoma (continued). "Collectively, N. sintenisii inhibited melanin synthesis and tyrosinase activity in B16 melanoma cells with no cytotoxic effects." (PMID 29755554, 2018). "Furthermore, in B16F10 melanoma cells treated with α-melanocyte-stimulating hormone, MHY1498 suppressed both melanin production and tyrosinase activity." (PMID 30551624, 2018). "Here we show that plumbagin significantly suppresses α-MSH-induced melanin biosynthesis in B16F10 mouse melanoma cells by inhibiting tyrosinase activity but that it does not inhibit MITF-mediated gene expression associated with melanogenesis." (PMID 28165370, 2017). "Cell lysates from tyrosinase-positive or tyrosinase-negative A375 melanoma cells were added to DC during the second maturation step." (PMID 28601925, 2017). "10-HDA significantly (p < 0.05) suppressed melanin synthesis and tyrosinase activity compared to the control of the non-treated B16F1 melanoma cells." (PMID 28793915, 2017). "Early in 2008, Guan and co-workers reported 2,3,5,4′-tetrahydroxystilbene-2-O-β-d-glucoside (THSG) as tyrosinase activator andmelanogenesisstimulator without cytotoxicity in B16 melanoma cells." (PMID 28777326, 2017). "Cordycepin was reported to inhibit α-MSH and IBMX induced melanin biosynthesis by inhibiting melanin synthesis related enzymes, such as tyrosinase, TRP-1, and TRP-2, suppressing CREB and MITF activity, and activating the PI3K/AKT pathway in B16F10 melanoma cells." (PMID 28114924, 2017). "In fact, it has been said that α-arbutin does not inhibit mushroom tyrosinase, but it is more potent than β-arbutin as an inhibitor of tyrosinase from B16 mouse melanoma." (PMID 28493937, 2017). "Pear fruit and its constituent PCA effectively inhibit cellular tyrosinase activity and expression through cAMP/CREB/MITF-mediated mechanism, which contributes to reduction in α-MSH-stimulated melanogenesis in mouse and human melanoma." (PMID 28825660, 2017). "In addition, we assayed its inhibitory effects on tyrosinase activity and melanin biosynthesis in B16F10 melanoma cells." (PMID 27801787, 2016). "Moreover, melanoma antigens such as tyrosine-related proteins TRP-1 and TRP-2, gp100 and melanoma antigen tyrosinase (Tyr) have been expressed from VEE vectors." (PMID 27827980, 2016). "Therefore, the purpose of the present study was to isolate a tyrosinase inhibitor from G. lucidum and evaluate its biological function in a B16F10 melanoma model in an effort to explain its skin-whitening effects." (PMID 27801787, 2016). "Using qRT-PCR, we successfully verified the deep sequencing results for two paRNAs: paTYR and paHSPC152 adjacent to the TYR and HSPC152 genes and further quantified them in several melanoma cell lines and biopsies, in normal human melanocytes and in immortalized or transformed melanocytes." (PMID 29657265, 2016). "Therefore, we treated B16-F10 murine melanoma cells with GFE-EA and investigated its down-regulation effects on secreted melanin, intracellular melanin amount per cell and cellular tyrosinase activity." (PMID 27611175, 2016). "Furthermore, to obtain a more objective and quantitative measurement of micrometastasis, we assessed the gene expression of melanoma-related genes (MITF, MLANA, TYR and TYRP) in RNA extracts from lungs and livers of experimental groups." (PMID 27120788, 2016). ", melanoma (Melan-A, human melanoma black-45, and tyrosinase), and carcinoma (cytokeratin) markers are typically absent." (PMID 27429816, 2016). "Moreover, this kind of therapy is very advantageous because all the melanoma cells treated with MTX are forced to switch into a MITF-M and tyrosinase-positive phenotype and become sensitive to TMECG." (PMID 25853464, 2015). "The underlying mechanism may involve the induction of ER stress and accumulation of unfolded proteins, such as tyrosinase (TYR) and tyrosinase-related protein 1 (TRP-1), two melanoma marker proteins." (PMID 25903364, 2015).